TRPM7 (transient receptor potential cation channel subfamily M member 7)
Diseases named in the same sentence as TRPM7 in open-access papers (continued):
Sharing a sentence is not in itself a finding about the gene and the disease.
preeclampsia (2 papers, 2019 to 2024). Preeclampsia is a hypertensive disorder of pregnancy that is characterized by new-onset hypertension with proteinuria presenting after 20 weeks of gestation, and depending on mild or severe forms may initially present with severe headache, visual disturbances, and hyperreflexia. "In a study examining placentas from women with preeclampsia compared to placentas from normotensive women, pre-eclamptic placentas had reduced expression of TRPM6 and TRPM7, which was linked to altered cellular Mg2+ homeostasis." (PMID 30995736, 2019). "We also highlight how interplay between TRPM7, Mg2+ and signaling kinases influences cell function in physiological and pathological conditions, such as cancer and preeclampsia." (PMID 30995736, 2019). "We hypothesize that placental TRPM7, which is downregulated in preeclampsia, interacted with MDMX during the overnight incubation with the immunoprecipitation beads stripping MDMX of Zn2+." (PMID 38594674, 2024).
prostate adenocarcinoma (2 papers, 2012 to 2020). "TRPM7 is reported to be overexpressed in human pulmonary adenocarcinoma, and pancreatic and prostate adenocarcinoma." (PMID 32907556, 2020). "Depletion of PRKAR2B, ADCK2, TRPM7 and TRIB2 significantly decreased HIF-1α accumulation in LNCaP, an androgen-sensitive human prostate adenocarcinoma cell line with low invasive potential." (PMID 22355351, 2012).
pulmonary fibrosis (2 papers, 2019 to 2022). Chronic progressive interstitial lung disorder characterized by the replacement of the lung tissue by connective tissue, leading to progressive dyspnea, respiratory failure, or right heart failure. "Overall, we uncover TRPM7 as a novel supporter of TGF-β1 signaling in pHPF and propose TRPM7 blockers as new candidates to control excessive ECM levels under pathophysiological conditions conducive to pulmonary fibrosis." (PMID 35864199, 2022). "Based on the current literature, we postulated that small-molecule TRPM7 blockers may represent new pulmonary fibrosis therapeutics." (PMID 35864199, 2022). "Thus, we identify a so far unappreciated role for the TRPM7 as a positive modulator of the plasmin system in pulmonary fibroblasts and propose TRPM7 blockers as new promising tools to treat pulmonary fibrosis." (PMID 35864199, 2022).
rectal cancer (2 papers, 2022 to 2024). A primary or metastatic malignant neoplasm that affects the rectum. "Our data showed that TRPM7 expression was higher in younger patients than that in older patients with rectal cancer." (PMID 36363540, 2022). "TRPM7 is closely related to the main genes involved in colorectal carcinogenesis, suggesting that it plays an important role in rectal cancer." (PMID 36363540, 2022). "Here, we analyzed clinicopathological and prognostic characteristics of TRPM7 expression and its correlation with the expression of other genes in colon and rectal cancer using TCGA data." (PMID 36363540, 2022). "Based on these data, we analyzed the clinical characteristics of TRPM7 expression in colon and rectal cancer." (PMID 36363540, 2022). "In present study, we demonstrated the clinical characteristics of TRPM7 in colon and rectal cancers using public data (TCGA) for the first time." (PMID 36363540, 2022). "This study suggest TRPM7 has a critical role in the pathogenesis of rectal cancer, and may become a potential biomarker and therapeutic target for cancer." (PMID 36363540, 2022). "Future studies are needed to provide deeper insights into the role of TRPM7 in rectal cancer." (PMID 36363540, 2022). "Notably, higher TRPM7 expression was observed in younger patients with rectal cancer (p < 0.001)." (PMID 36363540, 2022). "In conclusion, our study highlights TRPM7 expression in CRC, particularly in rectal cancer, as a potential genetic marker." (PMID 36363540, 2022). "Nevertheless, survival analysis showed that TRPM7 expression did not have any prognostic value in colon and rectal cancers." (PMID 38255793, 2024). "Survival analysis found that TRPM7 expression did not have any prognostic value in colon and rectal cancers." (PMID 36363540, 2022). "Interestingly, TRPM7 expression was positively correlated with APC and KRAS gene expression in rectal cancer." (PMID 36363540, 2022). "However, survival analysis showed no prognostic value for TRPM7 in colon and rectal cancers." (PMID 36363540, 2022).
renal cell carcinoma (2 papers, 2022 to 2024). "A prominent role of TRPM7 channels in the migration and invasion of human renal cell carcinoma cells via the Akt and Src pathways has been also suggested." (PMID 38255793, 2024). "An overexpression of TRPM7 in human renal cell carcinoma cell lines and tissues has been reported." (PMID 38255793, 2024).
T-cell leukemia (2 papers, 2014). A malignant disease of the T-lymphocytes in the bone marrow, thymus, and/or blood. "Pharmacological inhibition of TRPM7 by the channel blocker waixenicin A has also been shown to inhibit cell proliferation of rat basophilic and human Jurkat T-cell leukemia cells." (PMID 25277194, 2014).
type 2 diabetes (2 papers, 2009 to 2024). "We therefore conducted a prospective nested case-control study among postmenopausal women in the Women's Health Study to investigate the association between common variations of the TRPM6 and TRPM7 genes and the risk of type 2 diabetes." (PMID 19149903, 2009). "However, it is unclear whether common genetic variation in TRPM6 and TRPM7 contributes to risk of type 2 diabetes." (PMID 19149903, 2009).
Ureteral obstruction (2 papers, 2020). Obstruction of the flow of urine through the ureter. "NS8593 indeed suppressed TRPM7 protein expression in unilateral ureteral obstruction (UUO) kidneys, however, not back to the same level as seen in contralateral kidneys (CLK)." (PMID 32047249, 2020). "Using the unilateral ureteral obstruction (UUO) mouse model, we examined whether TRPM7 contributes to progressive renal damage and fibrosis." (PMID 32047249, 2020).
acral melanomas (1 paper, 2022). "In another cohort of 34 patients with acral melanomas, we found one tumor with an intrachromosomal rearrangement on chromosome 15 targeting the genes TRPM7 and MYO5A." (PMID 35053440, 2022). "In the Cancer Genome Atlas, we found one case of acral melanoma (TCGA-ER-A19T-01) harboring a strong focal amplification on chromosome 15 (orthologous to canine chromosome 30) encompassing the candidate oncogenes SPPL2A, USP8, TRPM7, and GABPB1." (PMID 35053440, 2022).
acute graft versus host disease (1 paper, 2017). A syndrome of immunologically mediated tissue damage that may occur following an allogeneic transplant, usually affecting the skin, liver, and GI tract. "We find that gut colonization by alloreactive T cells in acute graft-versus-host disease depends on TRPM7 kinase activity, indicating a therapeutic potential of kinase inhibitors in averting this condition." (PMID 29203869, 2017). "Notably, we find that the TRPM7 kinase activity promotes gut colonization by alloreactive T cells in acute graft-versus-host disease." (PMID 29203869, 2017). "Finally, our study demonstrates the importance of developing pharmacological inhibitors for TRPM7 kinase activity to prevent the devastating consequences of acute GVHD without affecting the development of immunosuppressive Treg cells." (PMID 29203869, 2017).
acute kidney injury (1 paper, 2018). Sudden and sustained deterioration of the kidney function characterized by decreased glomerular filtration rate, increased serum creatinine or oliguria. "For the first time, we demonstrated in details that TRPM7 from its expression and function is involved in not only IR-related acute kidney injury, but also the renoprotection of CHBP." (PMID 29615639, 2018). "Therefore, TRPM7 could be a potential biomarker for IR-induced acute kidney injury." (PMID 29615639, 2018).
adenovirus infection (1 paper, 2019). "In order to consolidate the function of TRPM7 in PASMCs, we performed the enforced overexpression of TRPM7 in PASMCs through adenovirus infection." (PMID 31219801, 2019).
alcohol abuse (1 paper, 2023). The use of alcoholic beverages to excess, either on individual occasions ("binge drinking") or as a regular practice. "In order to provide a translational value in clinically caring for PLWH with alcohol abuse, we proceeded to investigate the modulation of TRPM7 protein expression after EtOH and HIV viral protein treatments in human primary cultures." (PMID 36768230, 2023).
anaplastic astrocytoma (1 paper, 2020). "The Oncomine data revealed a significant increase in TRPM7 mRNA expression in anaplastic astrocytoma, diffuse astrocytoma, and GBM patients compared to that in normal brain tissues." (PMID 33381038, 2020). "Major findings from the current study include: 1) TRPM7 mRNA expression is significantly increased in anaplastic astrocytoma, diffuse astrocytoma, and GBM patients compared to that in healthy brain tissue controls." (PMID 33381038, 2020).
astrocytoma (1 paper, 2023). "TRPM7 and ALDH1 proteins were expressed in grade II astrocytoma, grade III astrocytoma, grade IV GBM, and normal tissues, which were localized in both cytoplasm and nucleus." (PMID 37642779, 2023).
autoimmune disease (1 paper, 2026). A disorder resulting from loss of function or tissue destruction of an organ or multiple organs, arising from humoral or cellular immune responses of the individual to their own tissue constituents. "While further research into TRPM7 and its effects on immune cell function including TRPM7 kinase-related signaling is needed, this study underlines TRPM7 as a possible druggable target in T-cell-dependent pro-inflammatory and autoimmune diseases." (PMID 41326173, 2026).
cardiomyopathy (1 paper, 2023). A disease of the heart muscle or myocardium proper. "TRPM7 might also be implicated in ventricular arrhythmias, since cardiac TRPM7 deletion in mice is associated with a high risk of developing cardiomyopathy, characterized by impaired repolarization and ventricular arrhythmias." (PMID 36818331, 2023).
cerebral (1 paper, 2020). "In the vascular system, TRPM7 inhibition reduced calcification in VSMCs21 and disruption of platelet TRPM7-kinase activity protected the brain from cerebral inflammation and thrombus formation." (PMID 31250885, 2020).
Cerebral degeneration (1 paper, 2018). "This indicates that over-activated TRPM7 channels can lead to cerebral degeneration via an influx of metal ions." (PMID 30486272, 2018).
channelopathies (1 paper, 2023). "The discovered structural mechanisms provide foundations for understanding the molecular basis of TRPM7 channelopathies and drug development." (PMID 37156763, 2023).
Cirrhosis (1 paper, 2023). A chronic disorder of the liver in which liver tissue becomes scarred and is partially replaced by regenerative nodules and fibrotic tissue resulting in loss of liver function. "Magnesium depletion and overexpression of its influx chanzyme TRPM7 in hepatocytes are associated with severity of hepatocyte injury and prognosis in cirrhosis." (PMID 37299589, 2023). "For these reasons, a relevant role of TRPM7 in the pathogenesis of liver disease and cirrhosis has been hypothesized." (PMID 37299589, 2023). "In conclusion, in the present study, we demonstrated that, in human liver affected by cirrhosis compared to normal liver, hepatocytes are Mg depleted and show an overexpression of TRPM7, the channel for magnesium entry, which is probably secondary to Mg depletion." (PMID 37299589, 2023).
Cognitive impairment (1 paper, 2022). Abnormal cognition is characterized by deficits in thinking, reasoning, or remembering. "In addition, increasing cleavage of TRPM7 α‐kinase by CD82 has been shown to induce numb phosphorylation at T346S348 and promoted Aβ secretion, which suggests that elevated CD82‐TRPM7‐Numb signal may be associated with cognitive impairment." (PMID 36401602, 2022).
colonic adenoma (1 paper, 2014). "Moreover, the epidemiological finding of the TRPM7 variant T1482I (previously identified in patients with neurodegenerative diseases) in association with dietary intake of Ca2+/Mg2+ and colonic adenoma/polyps supports further exploration of TRPM7 as a predictive biomarker of cancer." (PMID 25079291, 2014).
colorectal adenocarcinoma (1 paper, 2017). The most common type of colorectal carcinoma. "To establish a possible link between TRPM6, TRPM7, magnesium (Mg2+) and colon carcinogenesis, we first set out to characterize channel kinases in vitro using the human colorectal adenocarcinoma cell line HT-29." (PMID 28810912, 2017).
developmental delay (1 paper, 2024). "Our data indicate that individuals with TRPM7 missense variants can also present with global developmental delay, especially affecting motor skills and speech." (PMID 39099563, 2024). "In conclusion, we have identified three novel pathogenic TRPM7 missense variants in individuals with hypomagnesemia and developmental delay." (PMID 39099563, 2024). "It is therefore essential that TRPM7 variants are considered in the diagnosis of individuals with unsolved hypomagnesemia with or without developmental delay and ASD." (PMID 39099563, 2024). "By screening the TRPM7 gene in individuals with hypomagnesemia, developmental delay and/or ASD the diagnosis of these disorders can be improved and the phenotypic spectrum of TRPM7-related disorders can be expanded." (PMID 39099563, 2024).
endometrial carcinoma (1 paper, 2019). A malignant tumor arising from the epithelium that lines the cavity of the uterine body. "The purpose of the present study was to investigate the activity of TRPM2 and TRPM7 ion channels due to their close relationship with proliferation and migration mechanisms in endometrial hyperplasia and early stage endometrial cancer." (PMID 30997980, 2019). "In conclusion, in early stage endometrial cancers, a significant reduction in TRPM7 ion channel activity relative to endometrial hyperplasia may be a progression marker for endometrial hyperplasia independently of the atypia criteria." (PMID 30997980, 2019).
endometrium adenocarcinoma (1 paper, 2019). An adenocarcinoma arising from the uterine body cavity. "This study compared TRPM2 and TRPM7 ion channel gene expression and immunohistochemical staining in endometrial hyperplasia and endometrium adenocarcinoma." (PMID 30997980, 2019).
esophageal cancer (1 paper, 2019). A primary or metastatic malignant neoplasm involving the esophagus. "A recent research has revealed that TRPM7 displays a significantly higher level in esophageal cancer tissues and cell lines, but TRPM7 knockdown facilitates migration and invasion of esophageal cancer cells." (PMID 31519770, 2019).
experimental autoimmune encephalomyelitis (1 paper, 2019). An autoimmune demyelinating disease of the central nervous system that is produced experimentally in animals by the injection of homogenized brain or spinal cord in Freund's adjuvant. "Finally, it will be interesting to study whether astrocyte specific knockout of TRPM7 would alter the clinical symptoms in mice suffering from experimental autoimmune encephalomyelitis (EAE), the animal model for MS." (PMID 30453391, 2019).
fibrosarcoma (1 paper, 2023). A malignant mesenchymal fibroblastic neoplasm affecting the soft tissue and bone. "Compared with normal fibroblasts, fibrosarcoma cells exhibit lower TRPM7 (another TRPP channel) and RhoA activity and are less sensitive to fluid shear stress." (PMID 37864030, 2023). "Fibroblasts, but not the TRPM7-deficient fibrosarcoma cells, reverse their migration direction under 0.5 dyne/cm2 shear flow." (PMID 37864030, 2023). "For example, normal fibroblasts, but not fibrosarcoma cells, reverse the migration direction within the microchannels in response to fluid shear stress through TRPM7 and RhoA activities." (PMID 37864030, 2023).
Hip dysplasia (1 paper, 2026). The presence of developmental dysplasia of the hip. "We identified three genome-wide significant novel loci, COL11A2, CALN1 and TRPM7, associated with hip dysplasia without dislocation." (PMID 41912496, 2026).
hypercholesterolaemia (1 paper, 2020). "In addition to systemic inflammation, TRPM7+/Δkinase mice had hypercholesterolaemia with reduced HDL levels." (PMID 31250885, 2020).
Hypermagnesemia (1 paper, 2019). An abnormally increased magnesium concentration in the blood. "Therefore, the use of PPIs should be avoided in the treatment of patients with TRPM6/TRPM7 mutation to reduce the incidence of hypermagnesemia." (PMID 30921222, 2019).
hypopharyngeal squamous cell carcinoma (1 paper, 2013). "Evidence demonstrating the presence of TRPM7 in human hypopharyngeal squamous cell carcinoma FaDu cells, leads to the present study targeting TRPM7 with BZs." (PMID 23426784, 2013). "The present study shows that midazolam, a commonly-used anesthetic drug, inhibits the growth and proliferation of human hypopharyngeal squamous cell carcinoma FaDu cells via the suppression of TRPM7 expression." (PMID 23426784, 2013). "In summary, the present results demonstrate that targeting TRPM7 with the anesthetic midazolam inhibits the proliferation of human hypopharyngeal squamous cell carcinoma FaDu cells and this may be counteracted by the TRPM7 agonist bradykinin." (PMID 23426784, 2013).
injury (1 paper, 2023). Damage inflicted on the body as the direct or indirect result of an external force, with or without disruption of structural continuity. "The pathogenesis of APAP-mediated acute liver injury involves the activation of TRPV1, TRPV4, TRPC1, TRPM2, and TRPM7 channels, which trigger the influx of Ca2+ into hepatocytes and subsequent cellular damage." (PMID 37569884, 2023).
Insulin resistance (1 paper, 2023). Increased resistance towards insulin, that is, diminished effectiveness of insulin in reducing blood glucose levels. "To delineate the underlying mechanisms, we identified that TRPM7-induced rise in intracellular Ca2+ as a primary mechanism activated the TAK1-NF-κB cascade, and promoted adipose inflammation and insulin resistance." (PMID 36717580, 2023). "Adipose-selective ablation of TRPM7 protects mice from exacerbation of inflammation and insulin resistance upon dietary stress." (PMID 36717580, 2023). "The enhanced expression of TRPM7 in adipocytes promotes adipose tissue inflammation, resulting in glucose intolerant and insulin resistance." (PMID 36717580, 2023). "To gain a better understanding of the role of TRPM7 in insulin resistance, we measured ex vivo insulin action." (PMID 36717580, 2023).
intracerebral hemorrhage (1 paper, 2020). A cerebrovascular disorder characterized by bleeding into one or both cerebral hemispheres including the basal ganglia and the cerebral cortex. "In addition, miR21-5p can enhance MSCs survival and can be transported to neurons through exosomes derived from MSCs and that it can target transient receptor potential melastatin 7 (TRPM7) to alleviate neuronal injury following intracerebral hemorrhage." (PMID 33026076, 2020).
intraductal papillary mucinous neoplasm (1 paper, 2015). "In pancreatic intra-epithelial neoplasms (PanINs) and intraductal papillary mucinous neoplasm (IPMN), there is a moderate level of TRPM7 expression that appears to be localized on the plasma membrane." (PMID 25770184, 2015).